LATS2 (large tumor suppressor kinase 2)
Diseases named in the same sentence as LATS2 in open-access papers (continued):
Sharing a sentence is not in itself a finding about the gene and the disease.
breast carcinoma (continued). "We previously demonstrated that deletion of the Lats1 and Lats2 genes in luminal mammary cells induces luminal-basal plasticity and YAP/TAZ-mediated development of basal-like mammary carcinomas." (PMID 39953252, 2025). "For example, miR-372 promotes the proliferation of CRC, breast cancer, and gastric cancer cells by binding to target sites in the 3′-UTR of large tumor suppressor homolog 2 (LATS2)." (PMID 37445863, 2023). "Further, miR-135-b also targets large tumor suppressor kinase 2 (LATS2), a intermediator of Hippo signaling, and promotes cell proliferation in unstratified breast cancer patient tumors." (PMID 35327452, 2022). "We therefore conclude that RASSF1A executes its tumor-suppressor functions in ERα-driven breast cancer cells through LATS1 and LATS2, and that mutual interaction between RASSF1A and LATS1 and LATS2 are important for the suppression of ERα+ breast cancer." (PMID 34831091, 2021). "MicroRNA-135b binds to LATS2, a member of the hippo-YAP1 axis, inducing cell proliferation, migration, and invasion in breast cancer." (PMID 34082774, 2021). "Glycosylation of LATS2 inhibits its activity by interfering with the LATS2 and MOB1 interaction in breast cancer." (PMID 33081387, 2020). "In this study, we evaluated the effect of quinacrine on expression of LATS1, LATS2, and YAP genes of the Hippo signaling pathway and YAP level in human breast cancer stem cells (MDA-MB 231 cell line)." (PMID 33247672, 2020). "To further explore the impact of LATS2 down-regulation on human lumB cancer, we used our LATS2L signature to probe breast cancer cell lines in the Cancer Cell Line Encyclopedia." (PMID 30456386, 2018). "To gain insight into the impact of LATS1 and LATS2 deregulation on breast cancer, we examined the correlation between the expression levels of LATS1 and LATS2 in human breast cancer samples (TCGA- BRCA dataset)." (PMID 30456386, 2018). "FOXP3 has been reported as a suppressor gene in breast cancer and prostate cancer via repressing the expression of oncogene such as HER2, SKP2, p21, LATS2 and c-Myc." (PMID 28716029, 2017). "Some tumors such as breast cancer and astrocytoma have shown downregulation of LATS1 and LATS2 mRNA expression through promoter methylation." (PMID 26942001, 2016). "Meanwhile, Ring-finger E3 ligase SIAH1, activated by HIF-1, is required for the hypoxia-induced ubiquitination and proteasome-dependent degradation of LATS2 and trigger nuclear localization of TAZ, leading to the breast cancer stem cells (BCSCs) maintenance." (PMID 27042197, 2016). "In breast cancer and acute lymphoblastic leukemia (ALL), LATS2 mRNA is downregulated and has been suggested to be a tumor suppressor." (PMID 20932276, 2010). "Furthermore, our results support the notion that the Hippo pathway is important for the suppression of luminal breast cancers, and that the tumor-suppressor function of RASSF1A depends on LATS1 and LATS2." (PMID 34831091, 2021). "Moreover, deletion of Lats2 nearly abolished the death of cultured PyMT mouse tumor cells upon RGZ treatment, further confirming that sensitivity of lumB breast cancer cells to PPARγ activation is LATS2 dependent." (PMID 30456386, 2018). "Indeed, genes commonly down-regulated in both Lats2-CKO PyMT tumors and LATS2L lumB human breast cancers were significantly enriched for “PPAR signaling”, confirming the link between LATS2 and PPARγ activity in both mouse and human tumors." (PMID 30456386, 2018). "Compared with nondeleted littermate controls (WT-PyMT), deletion of Lats2 significantly augmented mammary tumor burden, formally validating the tumor suppressive function of LATS2 in mammary tumors." (PMID 30456386, 2018). "TAZ is also regulated post-translationally, as phosphorylation of TAZ by the kinase LATS1 or LATS2 blocks its nuclear localization and transcriptional activity and it is not clear whether or how inhibition by LATS1/2 is down-regulated in breast cancer." (PMID 25587023, 2014).
breast carcinoma (continued). "Whereas LATS1 protein was constitutively expressed at low levels, LATS2 protein was highly expressed under non-hypoxic conditions and expression was dramatically decreased under hypoxic conditions in the four breast cancer cell lines that were analyzed." (PMID 25587023, 2014). "In conclusion, our findings suggest that in breast cancer cells, miR-105-5p can be specifically internalized into exosomes and that exosomal miR-105-5p can be taken up by NFs and then promote NF-CAF transformation by inhibiting LATS2 and activating NF-κB signaling." (PMID 40151143, 2025). "Here we show that RASSF1A depends on LATS1 and LATS2 for the execution of its tumor-suppressor functions in ERα-driven breast cancer cells and suggests that the mutual interaction between RASSF1A and the Hippo-kinases LATS1 and LATS2 is important for the suppression of ERα+ breast cancers." (PMID 34831091, 2021). "To investigate whether LATS1 and/or LATS2 are indeed responsible for RASSF1A-mediated suppression of YAP1, ERα and FOXM1 expression in ERα+ breast cancer cells, we employed stable knockdown of either LATS1, LATS2 or LATS1+LATS2 in RASSF1A-conditional MCF7 cells." (PMID 34831091, 2021). "Hence, these two closely related paralogs play distinct roles in protection against breast cancer; tumors with reduced expression of either LATS1 or LATS2 may rewire signaling networks differently and thus respond differently to anticancer treatments." (PMID 30456386, 2018). "Notably, MIR22HG stabilized the expression of large tumor suppressor 2 (LATS2), which promoted the LATS2-dependent phosphorylation of YAP1 and suppressed the expression of its downstream target oncogenes, thereby inhibiting the proliferation and migration of breast cancer cells." (PMID 34446703, 2021). "In contrast, LATS2 overexpression did not reduce the viability of MDA-MB-468 cells, derived from basal-like breast cancer, suggesting a luminal cancer-specific proapoptotic role of LATS2." (PMID 30456386, 2018). "We demonstrated by Western blotting that LATS1, and not LATS2, was significantly decreased upon MG treatment (300 and 500 μM) in both glycolytic MDA-MB-231 and MDA-MB-468 and non-glycolytic MCF7 breast cancer cells." (PMID 27759563, 2016). "In addition, we derived a basal-like expression signature from human breast cancer samples (TCGA dataset, see the Materials and Methods section) and found it to be up-regulated selectively in the Lats1-CKO PyMT, but not Lats2-CKO tumors (each compared with WT-PyMT littermate control tumors)." (PMID 30456386, 2018).
lung cancer (36 papers, 2010 to 2025). A malignant neoplasm involving the lung. "To investigate the underlying mechanisms of miR-25 in enhancing lung cancer cell metastasis, we identified LATS2 as a novel target of miR-25." (PMID 31316723, 2019). "LATS2 overexpression was demonstrated to suppress lung cancer cell proliferation and induce NSCLC cell cycle arrest and apoptosis." (PMID 35902569, 2022). "It has been reported that LATS2 inhibits the growth of lung cancer cells by downregulating the cyclin E/CDK2 kinase activity." (PMID 32892482, 2020). "As expected, a luciferase reporter assay and western blot analysis identified that LATS2 was a direct target gene of miR-25 in lung cancer." (PMID 31316723, 2019). "We identified the large tumor suppressor homology 2 (LATS2) as a new target gene of miR-25 in lung cancer." (PMID 31316723, 2019). "Collectively, these data support that miR-25 is an important regulator of the key kinase LATS2 in the Hippo pathway and provided new insights into the upstream regulation of Hippo signaling in lung cancer." (PMID 31316723, 2019). "We first examined LATS2 mRNA expression in 15 pairs of lung cancer tissues and their adjacent normal tissues by qRT-PCR." (PMID 31316723, 2019). "Taken together, our findings demonstrate that miR-25 contribute to lung cancer cell proliferation and metastasis by targeting the LATS2/YAP signaling pathway, which implicate miR-25 as a promising therapeutic target for lung cancer metastasis." (PMID 31316723, 2019). "For example, lncRNA PVT1 was expressed at high levels in lung cancer cells, which promoted proliferation of non-small cell lung cancer cells by regulating LATS2 expression." (PMID 30925672, 2019). "Higher LATS2 levels in lung cancer patients contribute to better prognosis while forced overexpression of LATS2 in vitro reduces tumorigenicity of NSCLC." (PMID 29734788, 2018). "On the contrary, miR-31 acts as an oncogenic miRNA in human lung cancer tissues by targeting specific tumor suppressors LATS2 (large tumor suppressor kinase 2) and PPP2R2A (protein phosphatase 2, regulatory subunit B, alpha)." (PMID 29152108, 2017). "Such modulation of the LATS2/PPP2R2A pathway by miR-31 constitutes a novel growth regulator in lung cancer." (PMID 24744457, 2014). "Ectopic expression of LATS2 in human lung cancer cells induces apoptosis via down-regulation of apoptotic inhibitors such as Bcl-2 and Bcl-xL." (PMID 20932276, 2010). "The oncogenic effects of miR-31 in lung cancer cells were attributed to inhibition of large tumor suppressor 2 (LATS2) and PP2A regulatory subunit B alpha (PPP2R2A)." (PMID 21048943, 2010). "In lung cancer cell lines (A549 and H1299), overexpression of LATS2 induces apoptosis, while it rescues apoptosis induced by nocodazole in the U2OS cell line." (PMID 20932276, 2010). "MiR-762, MST1, LATS2, YAP mRNA and protein, TWIST1, and SMAD3 may be effective diagnostic biomarkers in both lung cancer patients and chronic inflammatory patients." (PMID 38589525, 2024). "Notably, a recent study has also revealed that overexpression of LATS2 can inhibit malignant features of lung cancer cells, suggesting that LATS2 acts as a tumour suppressor in lung cancer." (PMID 38652219, 2024). "Furthermore, WBP2 has been recently shown to associate with LATS2 and WWC3 to inhibit the Hippo tumor suppressor pathway in gastric and lung cancers, in turn limiting cancer proliferation and invasion." (PMID 34197030, 2022). "We found that LATS2 levels were lower in lung cancer tissues than in adjacent normal tissues." (PMID 31316723, 2019). "In our study, we identified that LATS2 was a direct target of miR-25 in lung cancer." (PMID 31316723, 2019). "Data from the Cancer Genome Atlas (TCGA) indicated that lung cancer patients (n = 573) with a high expression of LATS2 exerted higher overall survival rates than those (n = 572) with a low expression of LATS2, suggesting a tumor suppressive role for LATS2 in lung cancer." (PMID 31316723, 2019).
lung cancer (continued). "The methylation of LATS1/LATS2 has been demonstrated in Japanese lung cancer patients." (PMID 26942001, 2016). "The observed up-regulation of the proto-oncogene ect2 that plays a critical role in cytokinesis and repression of the tumor suppressor Lats2, which negatively regulates the cell cycle by controlling G1/S and/or G2/M transition, are important additional changes induced by c-Myc in lung cancer." (PMID 26427040, 2015). "The relative expression of miR-762, MST1, LATS2, YAP, TWIST1, and SMAD3 was determined in 50 lung cancer patients, 30 patients with chronic inflammatory diseases, and 20 healthy volunteers by real-time PCR." (PMID 38589525, 2024). "NSE protein is superior to YAP protein followed by miR-762, MST1, TWIST1, YAP gene, LATS2, and SMAD3 for the prediction of lung cancer." (PMID 38589525, 2024). "On the other hand, the expression of MST1, LATS2 and the concentration of YAP protein were significantly downregulated in lung cancer patients (P = 0.008, 0.008, 0.001, respectively) as well as chronic inflammatory patients (P ˂ 0.001)." (PMID 38589525, 2024). "It is reported that EZH2 directly interact with LATS2 and E‐cadherin promoter regions and activate H3K27 trimethylation modification in non‐small cell lung cancer 36 and gastric cancer." (PMID 33336896, 2021). "We showed that LATS2 was downregulated in tumor tissues of NSCLC patients and lung cancer cell lines, in agreement with a previous report." (PMID 31316723, 2019). "For instance, microRNA-135b promotes lung cancer metastasis by targeting tumour suppressor LZTS1 and multiple key components in the Hippo pathway such as LATS2, β-TrCP and NDR223." (PMID 26395400, 2015). "For example, miR-31 was demonstrated that overexpression of miR-31 led to increased growth rate by targeting suppressors, LATS2 and PPP2R2A in lung cancer." (PMID 25797269, 2015). "This is consistent with previous studies in LATS2-/- embryos and U2OS cells, but different from results obtained with lung cancer cells and Hela cells." (PMID 20932276, 2010). "Additionally, LINC00511 was also demonstrated to downregulate the expressions of KLF2 and LATS2 by promoting the binding of LSD1 to the promoter regions of LATS2 and KLF2 in lung cancer cells." (PMID 32713253, 2020). "LATS2 is reported as a target gene of miR-25 in ovarian cancer and gastric cancer, yet such a relationship in lung cancer has not been established." (PMID 31316723, 2019). "With 269 novel interactions, OncoPPi greatly expands the landscape of interactions among this selected set of lung cancer genes and defines interactions with potential significance for cancer PPI target discovery, such as CDK4/STK11, LATS2/RASSF1 and MYC/NSD3 (WHSC1L1)." (PMID 28205554, 2017). "More recently, factor-inhibiting hypoxia-inducible factor (FIH) was experimentally verified as the target of miR-31 in HNSCC cell and the tumor-suppressive genes, large tumor suppressor 2 (LATS2) and PP2A regulatory subunit B alpha isoform (PPP2R2A) were the targets of miR-31 in lung cancer." (PMID 21062447, 2010). "In lung cancer patients, there were significant negative correlations between miR-762 and each of MST1, LATS2, and YAP protein (P = 0.048, 0.010, ˂ 0.001, respectively)." (PMID 38589525, 2024). "MiR-762 has a significant negative correlation with MST1, LATS2, and YAP protein in lung cancer patients and with MST1 and LATS2 in chronic inflammatory patients." (PMID 38589525, 2024). "Some studies have shown that the expression of hsa-mir-139-5p in human lung cancer cell lines inhibits the activity of DICER1, but does not inhibit PPP2R2A or LATS2." (PMID 35794555, 2022).
non-small cell lung carcinoma (35 papers, 2016 to 2024). A group of at least three distinct histological types of lung cancer, including non-small cell squamous cell carcinoma, adenocarcinoma, and large cell carcinoma. "For example, lncRNA prostate cancer associated transcript 6 promotes non-small-cell lung cancer cell growth, migration and invasion by repressing the expression of large tumor suppressor kinase 2 via binding with the epigenetic repressor EZH2." (PMID 35291911, 2022). "Among these results, we selected LATS2 for further investigation because previous work had proved that miR-107 directly targeted LATS2 in non-small cell lung cancer." (PMID 34131399, 2021). "The literature has shown that miRNA-650 is able to serve as an oncogene and promote cell proliferation by directly targeting large tumor suppressor kinase 2 (LATS2) in non-small cell lung cancer formation and progression." (PMID 31623173, 2019). "A recent study has indicated that LATS2 negatively regulates the expression of matrix metalloproteinase-2 and -9 in non-small cell lung cancer (NSCLC)." (PMID 29212185, 2017). "LATS2 is as a poor prognostic marker in non-small cell lung cancer." (PMID 33839701, 2021). "lncRNA AGAP2-AS1 could bind with EZH2 and LSD1 and recruit them to KLF2 and LATS2 promoter regions to repress their transcription in non-small-cell lung cancer." (PMID 30069164, 2018). "Besides, it was reported recently that ALKBH5 could inhibit miR-107/LATS2-mediated YAP activity by inhibiting tumor growth in non-small cell lung cancer." (PMID 35279083, 2022). "In non-small-cell lung cancer, low expression of LATS2 may result in poor prognosis." (PMID 34824999, 2021). "Furthermore, it has also been demonstrated that EZH2 can repress the expression of large tumor-suppressor kinase 2 (LATS2) in non-small-cell lung cancer cells, and we hypothesize a similar action in FHF13." (PMID 32157157, 2020). "In a study of non-small-cell lung cancer, upregulation of SBF2-AS1 and AGAP2-AS1 promoted tumor-cell proliferation by negatively regulating p21, KLF2 and LATS2." (PMID 36673815, 2023). "LINC00511 downregulates LATS2 and KLF2 by combining EZH2 and LSD1 to promote the proliferation, migration, and invasion of non-small-cell lung cancer." (PMID 35664432, 2022). "Overall, our results demonstrated that non-small-cell lung cancer viability is regulated by ROCK1 and the LATS2-JNK pathway." (PMID 32554853, 2020). "In non-small cell lung cancer, lncRNA AGAP2-AS1 acts as an oncogene that inhibits the expression of large tumor suppressor kinase 2 (LATS2) and Kruppel-like factor 2 (KLF2) via interacting with EZH2 and LSD1." (PMID 32202509, 2020). "For example, it can promote non-small cell lung cancer cell proliferation by recruiting EZH2 to the large tumor suppressor kinase 2 (LATS2) promoter and represses LATS2 transcription." (PMID 29244840, 2017). "In non-small-cell lung cancer cells, upregulated long non-coding RNA AGAP2-AS1 represses LATS2 and KLF2 expression through interacting with EZH2 and LSD1." (PMID 29050269, 2017). "For example, lncRNA AGAP2-AS1 has been demonstrated to recruit the enhancers of zeste homolog 2 (EZH2) and LSD1 to the promoter regions of KLF2 and large tumor suppressor 2 (LATS2), thus suppressing the transcription of KLF2 and LATS2 and promoting the progression of non-small cell lung cancer." (PMID 38516191, 2024). "It was also reported that the upregulation of the long non-coding RNA AGAP2-AS1 facilitates cell proliferation, migration and invasion, and inhibits cell apoptosis; it also represses LATS2 and KLF2 expression through its interaction with EZH2 and LSD1 in non-small-cell lung cancer cells." (PMID 27906682, 2017).